OSBPL3 (oxysterol binding protein like 3)
Diseases named in the same sentence as OSBPL3 in open-access papers (continued):
Sharing a sentence is not in itself a finding about the gene and the disease.
tumor (continued). "We also first presented evidence that the tumor with high expression of OSBPL3 had higher TMB, which is one of the important prediction markers of the efficacy of tumor immunotherapy." (PMID 34738015, 2021). "The expression of OSBPL3 mRNA was significantly higher in tumor tissues than in normal tissues, consistent with the in silico analysis using the TCGA dataset (Mann–Whitney U test, p < 0.001)." (PMID 34584127, 2021). "We found that elevated ERO1A, OSBPL3 and IFI44L protein expression in tumor tissues was significantly associated with late T stage which represent depth of tumor invasion and late TNM stage." (PMID 28881752, 2017). "It has been suggested that OSBPL3 is an R-Ras interacting oxysterol-binding protein homolog that regulates cell adhesion and plays a role in promoting tumor cell proliferation, migration and invasion, and evidence was obtained that the OSBPL3-VAPA complex stimulates R-Ras signaling." (PMID 36517805, 2022). "To evaluate whether phosphorylation of OSBPL3 has an effect on tumors, we compared the differences in OSBPL3 phosphorylation levels between primary tumor and normal tissues." (PMID 34738015, 2021). "OSBPL3 protein is an intracellular lipid receptor of the oxysterol-binding protein superfamily, which participates in some pathological and physiological processes in tumor progression." (PMID 34738015, 2021). "In summary, our studies have demonstrated that OSBPL3 plays an important role in tumorigenesis from the perspective of public databases and clinical tumor samples and is potentially a novel and specific target for cancers, which comprehensively provides insights for further investigation." (PMID 34738015, 2021). "Furthermore, our clinical analysis showed that high OSBPL3 expression was correlated with tumor pathological aggressiveness and progression and was an independent factor for a poor prognosis in GC patients." (PMID 34584127, 2021). "Immunohistochemistry of CRC tumor tissues confirmed that OSBPL3 is up-regulated in CRC." (PMID 34308980, 2021). "Therefore, OSBPL3 promotes tumor growth and cell cycle progression at least partially via activation of the R-Ras/Akt signaling pathway in GC." (PMID 34584127, 2021). "Notably, the OSBPL3 gene is located on chromosome 7 that was remarkably amplified in the tumor tissues of GC patients from TCGA, suggesting that OSBPL3 should be a candidate driver gene in GC." (PMID 34584127, 2021). "The results showed that OSBPL3 was expressed at abnormally high levels in these tumor biopsies." (PMID 34738015, 2021). "Elevated ERO1A, OSBPL3 and IFI44L protein expression in tumor tissues may cause patients’ median survival time 18.83%-44.07% (ERO1A:44.07%, OSBPL3: 18.83%and IFI44L, 42.37%) shorter than patients who without." (PMID 28881752, 2017). "Additionally, OSBPL3 expression was negatively correlated with the degree of tumor differentiation." (PMID 36517805, 2022). "Notably, we found a strong concordance between OSBPL3 overexpression and high Ki-67 expression in tumor cells within most tissue sections that showed immunoreactivity for both OSBPL3 and Ki-67, and OSBPL3 overexpression was strongly associated with high Ki-67 expression (P < 0.05)." (PMID 36517805, 2022). "Although there are few studies on the expression and role of OSBPL3 in tumors, our study shows that OSBPL3 was highly expressed in multiple human tumors compared with normal tissues from both the detection of the TCGA database and experiments of tissues of tumor patients." (PMID 34738015, 2021). "The results displayed that the expressions of OSBPL3, OSBPL5, SOBPL7, and OSBPL10 were significantly correlated with tumor purity, B cell, CD8 + T cells, CD4 + T cells, macrophages, neutrophils, and dendritic cells infiltration levels." (PMID 36918840, 2023). "As to the protein expression, OSBPL2 and OSBPL3 were significantly elevated and OSBPL5, OSBPL6, OSBPL9, OSBPL10, OSBPL11 were downregulated in tumor samples." (PMID 36918840, 2023).
tumor (continued). "The results demonstrated that the protein expressions of OSBPL2 and OSBPL3 were elevated while OSBPL5, OSBPL6, OSBPL9, OSBPL10, and OSBPL11 were lowly expressed in tumor samples." (PMID 36918840, 2023). "For further exploring the relationship of OSBPL3 with the TME, we analyzed the immune cells in the tumor microenvironment." (PMID 37550605, 2023). "Furthermore, although there is a correlation between KRAS mutations and OSBPL3, it is unclear whether OSBPL3 affects tumor biology regardless of KRAS status." (PMID 36517805, 2022). "The expression level of OSBPL3 in CRC was found to be positively correlated with poor differentiation, tumor-node-metastasis (TNM) stage and Dukes stage." (PMID 36517805, 2022). "The MIR4435-2HG- and ELFN1-AS1-associated ceRNA subnetworks affected and regulated the expression of the COL5A2, LOX, OSBPL3, PLAU, VCAN, SRM, and E2F1 target genes and were found to be related to prognosis and tumor-infiltrating immune cell types." (PMID 33750326, 2021).
cancer (11 papers, 2017 to 2024). A tumor composed of atypical neoplastic, often pleomorphic cells that invade other tissues. "A high abundance of intra-tumoral OSBPL3 cells had prolonged survival that are seen in a significant proportion of cancer patients, and it seems likely that the mutation, phosphorylation, immune infiltration, and cell membrane pathways of OSBPL3 affect the disease forward." (PMID 34738015, 2021). "OSBPL3 is the most-studied gene family member and the main one to be associated with cancers." (PMID 34829830, 2021). "Differential analysis of OSBPL3 was performed in pan-cancer, and the correlation between clinical stage and OSBPL3 was analyzed." (PMID 37550605, 2023). "Immunohistochemical assays of 92 CRC samples also showed that OSBPL3 were highly expressed in cancer tissues (P < 0.0001)." (PMID 36517805, 2022). "qRT-PCR of paraffin specimens from 78 CRC patient tissues and adjacent normal tissues showed that OSBPL3 mRNA levels were significantly higher in cancer tissues than in normal tissues (P < 0.0001)." (PMID 36517805, 2022). "To analyze the relationship between OSBPL3 and immune checkpoint genes, we extracted and calculated more than 40 common immune checkpoint genes in diverse cancer types of TCGA." (PMID 34738015, 2021). "We show a general high level of OSBPL3 expression in major cancers compared with normal tissues from multiple databases and cancer biopsies." (PMID 34738015, 2021). "Although the role and interaction between OSBPL3 and immune infiltration need more in-depth molecular experimental verification, our large sample analysis and prediction of cancer database validation play a positive and hint role." (PMID 34738015, 2021). "Our lab is focusing and trying to clarify the role of OSBPL3 at both cellular and molecular levels in different types of cancers." (PMID 34738015, 2021). "We also performed meta-analysis of the correlation between OSBPL3 expression and prognosis with different cancers using the Kaplan–Meier plotter." (PMID 34738015, 2021). "It has been reported that OSBPL3 influences cell adhesion by regulating R-Ras activity and is overexpressed in several cancers." (PMID 28881752, 2017). "Thus, we explored the relationship between the OSBPL3 expression level and the active immune cells in different cancer types of TCGA." (PMID 34738015, 2021). "Using multiple bioinformatic analyses, we revealed that the molecular biological functions of OSBPLs family genes in PDAC, especially OSBPL3, might provide a novel mechanism in the tumorigenesis and cancer immunology of PDAC." (PMID 34829830, 2021). "Furthermore, we identified the mRNA expression of OSBPL3 across different types of human cancers and the corresponding normal tissues from the Oncomine database." (PMID 34738015, 2021). "Thus, the current clinical evidence still cannot support the role of OSBPL3 expression with the clinical outcome in different cancers, and more sample sizes are needed for exploration and confirmation." (PMID 34738015, 2021). "In this study, we aimed to explore the roles of the human OSBPL3 gene in different cancers." (PMID 34738015, 2021). "Next, we evaluated the expression status of OSBPL3 across various cancers from the TCGA project." (PMID 34738015, 2021). "Finally, we investigated the expression level of OSBPL3 and its prognostic significance across multiple cancers using TCGA data." (PMID 34584127, 2021). "Thus, we aimed to systematic explore the potential oncogenic roles of OSBPL3 across thirty-three tumors using multiple web-based and publicly available tools, including the Cancer Genome Atlas, Gene Expression Omnibus, Genotype-Tissue Expression, cBioPortal, and Human Protein Atlas database." (PMID 34738015, 2021).
cancer (continued). "This is the first systematic pan-cancer analysis, to our knowledge, to comprehensively summarize the molecular features, clinical prognosis, and mechanisms characterizing the presentation of the OSBPL3 gene and its impact on the process of tumorigenesis in a total of 33 different tumors." (PMID 34738015, 2021). "In the weighted gene correlation network analysis (WGCNA) study, OSBPL3 was identified as a pivotal gene in CRC, with upregulated expression in cancer tissues, and its high expression correlated with a poor prognosis in CRC." (PMID 36517805, 2022). "We also checked the protein and mRNA expression levels of OSBPL3 in four cancer cells (breast, lung, colon, and liver) and the protein expression in all types of human cancer cells from the CCLE dataset, and the results showed that OSBPL3 had high expression levels in cancer cell lines." (PMID 34738015, 2021). "However, there has been little clear evidence about the expression and role of OSBPL3 in tumors, and still, there is no pan-cancer study on the relationship between OSBPL3 and various cancers." (PMID 34738015, 2021). "Moreover, immunohistochemical analysis revealed that OSBPL3 staining intensity was stronger in cancer cells than in normal cells." (PMID 34584127, 2021).
OSBPL3 also shares sentences with these, for which no sentence is quoted: bladder cancer (4 papers); colon adenocarcinoma (3); infection (3); lung adenocarcinoma (3); B-cell lymphoma (2); adenocarcinoma (1); bladder tumors (1); digestive system carcinoma (1); esophageal carcinoma (1); fatty liver disease (1); head and neck squamous cell carcinoma (1); HIV-1 infection (1); Huntington disease (1); invasive carcinoma (1); leukemia (1); liver disease (1); lung squamous cell carcinoma (1); lymphoma (1); melanoma (1); metabolic (1); metastasis (1); metastatic tumors (1); neurodegenerative disease (1); ovarian carcinoma (1); pancreatic adenocarcinoma (1); Parkinson disease (1); prostate adenocarcinoma (1); rectum adenocarcinoma (1); schizophrenia (1); stomach adenocarcinoma (1).
A further 6 diseases each share a sentence with OSBPL3 in 1 paper.